RN7SL706P (RNA, 7SL, cytoplasmic 706, pseudogene)
Gene: Miscellaneous RNA gene on chromosome 14 (68,149,617 to 68,149,908, reverse strand). Ensembl gene ENSG00000244677.
Homologues: Orthologues: chimpanzee Metazoa_SRP (98% identical), macaque Metazoa_SRP (91% identical), dog Metazoa_SRP (66% identical). Paralogues in human: RN7SL714P (79% identical), RN7SL1 (78% identical), RN7SL2 (78% identical), RN7SL597P (78% identical), RN7SL788P (77% identical), RN7SL3 (77% identical), RN7SL660P (77% identical), RN7SL301P (76% identical), RN7SL709P (76% identical), RN7SL786P (76% identical), Metazoa_SRP (76% identical), RN7SL126P (76% identical), and 702 more.